CCR2 (C-C motif chemokine receptor 2)
Diseases named in the same sentence as CCR2 in open-access papers (continued):
Sharing a sentence is not in itself a finding about the gene and the disease.
tumor (continued). "Production of CCL2, which could induce a large amount of accumulation of MDSCs through CCR2, is strongly increased in tumor-bearing mice, and nestin+ splenocytes clearly participate in the increase in chemokine production in tumor- bearing hosts." (PMID 26161081, 2015). "Our results also indicate an increase of CCR2 in tumor-adjacent skin." (PMID 26413810, 2015). "Tumor infiltration of TAMs is often mastered by the Ccl2 chemokine that attracts Ccr2+ monocytes circulating in the blood, but in this study the expression of Ccl2 mRNA and its encoded protein MCP-1 in tumors were not modulated by treatment and hence cannot explain the effects on TAMs." (PMID 26673090, 2015). "The recruitment of these MDSC subtypes to tumor sites is mediated by chemokines highly expressed by tumor-associated neutrophils, including CXCR2 and CXCR4, and chemokines over-expressed by tumor infiltrating macrophages, including CCR2, CCR5, CXCR4 and CX3CR1." (PMID 26462153, 2015). "It is also reported that genetic depletion of CCR2+ monocytes (CD11b+Ly6C+) enhances accumulation of adoptively transferred CD8+ T cells in the primary tumor and thereby augments therapeutic effect of the adoptive T-cell therapy on the tumor growth in a melanoma model." (PMID 26275794, 2015). "Collectively, these data imply that therapeutic inhibition of CCR1 and CCR2 could be a novel strategy to prevent metastatic tumor growth." (PMID 26275794, 2015). "As CCL2 is a chemotactive factor for monocytes and could be integral in the recruitment of macrophages to the site of tumors development, we tested whether ablation of CCL2/CCR2 signaling affected tumor growth in a syngeneic transplant model." (PMID 25505466, 2014). "CC chemokine ligand 2 (CCL2) is a major chemoattractant for tumor-associated monocytes; however, TEMs do not express the receptor CCR2 on their surface." (PMID 24809734, 2014). "As CCR2 expression has a major role in regulating both the mobilization of monocytes from BM to the blood and homing to tumor 36,51,52, we measured CCR2 expression on MDSCs in the tumor microenvironment of silibinin-treated mice." (PMID 24574320, 2014). "Also, OCs in the tumor microenvironment sustain MM cell proliferation through production of chemokine that activate CCR2 on tumor cells." (PMID 25110692, 2014). "Furthermore, we successfully provided experimental evidence that the suppression of tumor growth mediated by CCR2 and WT1-siTCR double-transfected effector T cells was more effective than that mediated by WT1-siTCR single-transfected cells." (PMID 23441216, 2013). "Importantly, combined targeting of PCa AR (with AR-siRNA) and anti-CCL2/CCR2 axis (with CCR2atg) notably suppressed the growth of orthotopic TRAMP-C1 tumours (siAR veh vs. siAR CCR2atg, p = 0.018)." (PMID 23982944, 2013). "Thus, our results suggest that combined blockade of prostate AR and anti-CCL2/CCR2 signalling reduced primary tumour growth and distant metastases (siAR veh vs. siAR CCR2atg, p = 0.003)." (PMID 23982944, 2013). "One of the intriguing observations of the current manuscript is that in the growth kinetics of CCR2+ tumor implanted in CCR2−/− mice is comparable with the one developed in CCR2+ mice, whereas there is a huge reduction in illumination as observed by CCCD camera." (PMID 22279523, 2012). "Taken together, these results show that CCR2−/− mice display a reduced development of the CCR2+ primary tumor, as determined by tumor cell viability and spread in various ograns, but this reduced enzymatic activity was not correlated with the primary tumor size." (PMID 22279523, 2012). "At the tumor site CCR2 is expressed on invading tumor cells, the endothelium, and TAMs." (PMID 22279523, 2012). "However, the repeated treatment with of the CCR2-Ig not only further suppressed luciferase activity (p<0.01), but also led to a significant inhibition in tumor size (day 65, 227±19 compared to 770±65 mm3, p<0.001)." (PMID 22279523, 2012).
tumor (continued). "Finally a soluble CCR2-Ig that selectively neutralizes CCL2 was then used to determine the direct contribution of the autocrine interaction of CCL2-CCR2 on the cancer cells to tumor growth." (PMID 22279523, 2012). "We showed that only BM cells from CCR2+ mice could fully restore tumor development, implicating for the pivotal role of the CCR2+ BM cells in supporting tumor development and angiogenesis." (PMID 22279523, 2012). "This further emphasizes the role of CCR2+ BM derived cells in tumor development and survival." (PMID 22279523, 2012). "CCR2 expression by T-cell lines established from tumor infiltrating lymphocytes of CRC tissues." (PMID 21450101, 2011). "Our data demonstrate that GMME1 is a fusokine with a potent, CCR2 receptor-mediated pro-apoptotic effect on tumor cells and could be exploited as a novel biological therapy for CCR2+ malignancies including lymphoid and central nervous system malignancies." (PMID 21943176, 2011). "Also, Ab to CCR2 in the separating layer of collagen and fibroblasts blocked the migration of CTLs toward tumor cells and subsequently inhibited tumor cell apoptosis." (PMID 21450101, 2011). "Identification of tumor cells secreting CCL2 or T-cells expressing CCR2 in the tumor microenvironment could be a useful prognostic marker in CRC patients." (PMID 21450101, 2011). "On the basis of these findings, we propose that CCL2/CCR2 axis may be an important signaling pathway for MDSC recruitment to tumor microenvironment." (PMID 20111717, 2010). "In conclusion, we demonstrate herein that tumor cell-produced hBD-3 functions as a chemoattractant for recruitment of TAMs in the development of tumors and that hBD-3 chemoattracts monocytes/macrophages via the chemokine receptor CCR2." (PMID 20544025, 2010). "Collectively, these results indicate that hBD-3 utilizes CCR2 to regulate monocyte/macrophage trafficking and may act as a tumor cell-produced chemoattractant to recruit TAMs." (PMID 20544025, 2010). "Therefore, therapeutics that actively target CCR2+ TAMs may be strategically used to optimize the subversion of tumor immunosuppression, thereby effectively combating post-iIRE tumor recurrence." (PMID 40700478, 2025). "Loss of CCR2 also decreased the frequency of OVA-specific T cells in IFNγRKO-tumour bearing mice compared with WT mice, which indicates that monocyte recruitment is necessary for the recruitment and/or retention of antigen/tumour-specific CD8+ T cells in IFNγ-insensitive tumours." (PMID 39746898, 2025). "The quantitative analysis of CCR2 protein signal in marker-defined tumor tissue compartments showed significantly higher levels in CD11b+ myeloid cells than in CK− (nontumor) stromal areas and CK+ cancer cell nests; and this was consistent across the different tumor types analyzed." (PMID 39918395, 2025). "Moreover, after accumulation in the tumoral regions due to CCR2 targeting, the drug could be released within the acidic tumor microenvironment, thus enhancing treatment efficacy." (PMID 39376728, 2024). "In solid tumor TMEs, CCL2 can interact with its receptors to recruit CCR2+ TAMs, MDSCs, and Th2 cells, creating an immunosuppressive microenvironment that favors tumor progression and accelerates the colonization and growth of metastatic tumor cells, thus contributing to tumor development." (PMID 38769475, 2024). "Subsequently, to verify whether MI-induced tumor growth requires increased Ly6Chi monocyte availability and recruitment, a C-C chemokine receptor type 2 (CCR2)-diphtheria toxin receptor mouse model was established, in which monocytes were eliminated 7 days after MI or sham surgery." (PMID 39634266, 2024). "Therefore, targeting CCL2/CCR2 is a feasible anti-tumor treatment strategy." (PMID 37138860, 2023).
tumor (continued). "The question remains of whether Ly6C+ monocytes that still infiltrate into GBM in CCR2-deficient tumor-bearing mice express CCR2 and whether a subset exists that does not express CCR2, thereby negating any positive survival benefit in tumor-bearing mice." (PMID 36594465, 2023). "Targeting CCL2/CCR2 may also be a powerful measure for inhibiting tumor-promoting myelopoiesis." (PMID 37415162, 2023). "Furthermore, CCL2 inhibited adrenomedullin formation in tumor cells through its receptor CCR2." (PMID 36374225, 2023). "Therefore, taken together, it may be suggested that CVC can be a promising agent to prevent the progression of the tumor through inhibition of the CCR2_CCL2 signaling pathway." (PMID 37325423, 2023). "In addition, CCR2 expression in different tumor tissues may result in varying responses to CCR2 axis-targeted therapy." (PMID 37598273, 2023). "Finally, significant downregulation of Ccr2 in c-Myb induced tumor cells was detected." (PMID 37478172, 2023). "Therefore, CCL2/CCR2 inhibitors in combination with radiotherapy may be an efficient approach for improving the therapeutic effects of radiotherapy in tumor treatment." (PMID 36845095, 2023). "Importantly, inhibition of CCR2 partially attenuated FAM171B-induced tumor progression." (PMID 37915048, 2023). "Neither genetic deficiency of CCR2 nor a small-molecule inhibitor of CCR2 (CCX872) showed any efficacy in extending the survival time of tumor-bearing mice compared with WT or vehicle-treated mice, despite significant reductions of CCR2+ monocyte and CD45+CD11B+ myeloid infiltration into tumors." (PMID 36594465, 2023). "CCL2 is a chemokine that regulates monocyte and macrophage migration, and the CCL2/CCR2 axis has been shown to have multiple pro-tumor effects, ranging from mediating tumor growth and angiogenesis to recruiting and usurping host stromal cells to support tumor progression." (PMID 36045408, 2022). "However, the combination therapy of RT + αPD-1 + CCR2/5i led to better survival and tumor control." (PMID 35404390, 2022). "In addition, CCR2+ MDSCs are reported to increase tumor growth in mice bearing colorectal tumors." (PMID 35122833, 2022). "Therefore, we further explored whether the addition of RT to the triple combination of CCR2/5i + αPD-1 + GVAX could effectively slow tumor growth in a PDAC orthotopic murine model, which better resembles human PDAC." (PMID 35404390, 2022). "As several anti-CCR2 Abs are under development, it would be of interest whether anti-tumor efficacy links to their cell depleting property, and whether the depleting effect of anti-CCR2 Abs could be enhanced by antibody drug conjugation via antibody-guided delivery of cytotoxic drugs." (PMID 34804061, 2021). "Irbesartan suppressed MCP-1 production and the accumulation of Ly6C+CCR2+ monocytes and fibrocytes in the inflamed colon, downregulated the expression of type 1 collagen and matrix metalloproteinase 9 and inhibited the development of intestinal fibrosis and tumours." (PMID 34620946, 2021). "Furthermore, MFs with a more pro-inflammatory CCR2+ phenotype are rather localized perivascularly and in the peritumoral stroma, contributing to neoangiogenesis and the pro-inflammatory tumor microenvironment, while M2-like CCR2− TAMs are rather located in hypoxic areas and cancer nests." (PMID 34831182, 2021). "However, CCR2 also promotes T-cell recruitment, indicating that CCR2 blockade might affect T-cell migration to the tumor." (PMID 34065010, 2021). "Studies have shown that CCR2+ TAMs, CAFs, and cancer-associated adipocytes serve as additional sources of CCL2; these findings demonstrate the non-canonical roles of CCL2 in fibrosis generation, mesenchymal–epithelial transition, paracrine-induced tumor invasion, and angiogenesis." (PMID 34386431, 2021). "Importantly, CCR2 preferentially mediates tissue homing of Tregs including tumor tissue." (PMID 34804061, 2021).
tumor (continued). "Thus, targeting the CCL2/CCR2 axis may be a plausible avenue in cancer therapy, particularly for many solid tumors belonging to the “cold tumor” family." (PMID 34804061, 2021). "Together with our previous data, the present results suggest that the blockade of MCP-1/CCR2 pathway by irbesartan reduces the accumulation of fibrocytes into the inflamed colon and might inhibit tumour progression through the reduction of Col I and MMP-9 production." (PMID 34620946, 2021). "However, both the CCR2/CCL2 axis and neutrophils are reported to be ‘pro-tumor’ and therefore systemic treatment targeting neutrophils or the CCR2/CCL2 axis in humans may be particularly beneficial in that they decrease tumor size and abrogate CNS dysfunction." (PMID 32391790, 2020). "Therefore, diminishing the CCL2 and CCR2 interaction through the mTOR cascade may reduce TAMs recruitment and chemotaxis, subsequently promoting the anti-tumor effect of CD8+ T cells in TME." (PMID 32483450, 2020). "Hence, there may be clinical utility by combining currently approved anti-PD-1 mAb with targeting of CCR2/MCP-1 so as to overcome multiple mechanisms of tumor immune evasion." (PMID 33322474, 2020). "In addition, the importance of chemokines and their receptors in regulating anti-tumor immunity and tumor metastases were recently reviewed, including the dominant role of CCR2 in promoting recruitment of monocytes with pro-tumorigenic and pro-metastatic activities." (PMID 33322474, 2020). "Of note, an increased expression of IL-17 (IL-17RA), IL-8 (CXCR1) and CCL2 (CCR2) receptors was also observed on M-DM exposed to CM from bcl-2 overexpressing clone, suggesting a larger impact of cancer cell-specific bcl-2 on the interplay between the tumor and the stromal compartment." (PMID 32269145, 2020). "Moreover, we investigated whether blockade of the CCL2/CCR2 axis by CCR2 specific antagonist (RS504393) could inhibit the tumorigenicity of SACC cells in the xenograft tumor model." (PMID 31024838, 2019). "So far, few works support that TAM can be composed of newly recruited MoD-TAM mostly in a CCR2-dependent manner, but also ResTAM of embryonic origin (EmD-ResTAM) or arising from adult hematopoiesis (MoD-ResTAM) that locally proliferate and accumulate with tumor expansion." (PMID 31417566, 2019). "In addition, the tumor‐promoting effect of senescent stromal cells seen in experimental tumor models in mice could also be reduced by administration of the CCR2 antagonist in vivo." (PMID 31545552, 2019). "In addition, we demonstrated that blocking CCR2 with specific antagonist might be a salvage option to inhibit the residual tumor and overcome the resistance of anti-PD-1 therapy." (PMID 31780645, 2019). "To further demonstrate the unique cross-priming capacity of APCs derived from CCR2+HSCs, we isolated antigen presenting cells directly from the tumors of mice receiving adoptive cellular therapy and used them as a cellular vaccine in recipient mice receiving DsRed+ tumor-reactive T cells." (PMID 30333482, 2018). "Thus, MCP-1/CCL2/CCR2 signaling is important in the attraction of MSCs to irradiated tumor cells." (PMID 29615915, 2018). "Moreover, tumor size and CCR-2 expression were independent prognostic factors for MFS." (PMID 28420351, 2017). "Therefore, the CCL2/CCR2 reaction may have dual context-dependent effects in tumorigenesis: promoting the metastasis of tumors and providing anti-tumor effects at the same time." (PMID 28424406, 2017). "Therefore, the blockade of CCR2 may decrease the recruitment of immunosuppressive cells to the tumor microenvironment and thereby prevent tumor progression." (PMID 28424406, 2017). "This may activate CCL2/CCR2 signaling pathway and is important in promoting tumor growth." (PMID 28611777, 2017).
tumor (continued). "To further examine whether the involvement of CCR2-expressing myeloid cells in radioresistance can be translated into a clinically relevant strategy, we attempted to neutralize CCL2 in tumor studies because it is one of the chemokines proposed to attract CCR2+ cells to tissues and tumors." (PMID 29170400, 2017). "Thus, the lower frequency of CCR2+ T lymphocytes in carcinoma tissues might be a result of tumor immune surveillance escaping mechanisms." (PMID 29020986, 2017). "Thus, we speculate that the CCR2 high expression in tumor microenvironment was an indicator for high M2 infiltration and correlated with tumor progression." (PMID 26992207, 2016). "Because tumor growth can be affected by blood supply, we tested whether angiogenesis was altered in the various genetic backgrounds by examining tissue microarrays and slides using tumors isolated from neu+, neu+Ccl2-/-, and neu+Ccr2-/- mice at different ages." (PMID 27820834, 2016). "Moreover, hBD3 in oral tumor microenvironment could traffick CCR2 positive tumor-associated macrophages (TAM), which are known to generate an inflammatory tumor microenvironment and promote tumor aggressiveness." (PMID 27713149, 2016). "Therefore, the CCR2 positive cells in tumor tissues may TAMs, MDSCs, MSLCs or some bone morrow-derived fibroblasts." (PMID 26992207, 2016). "Notably, the migration to tumor of MDSCs depended mainly on CCL2/CCR2 pathway." (PMID 26992207, 2016). "Moreover, it is also important to establish whether inhibition of CCL2 had distinct effects compared to CCR2 inhibition, and if interference of both can lead to better anti-tumor responses in clinical trials." (PMID 26885690, 2016). "However, CCR2 deficiency results in the conversion of the MDSC phenotype from macrophage lineage to neutrophil lineage without affecting tumor growth." (PMID 24966464, 2014). "We next generated Tg-Braf/Ccr2-DTR mice to examine whether TAMs are required for tumor maintenance." (PMID 23372702, 2013). "Tumor cells, fibroblasts, and stromal cells often secrete high levels of CCL2, which attracts CCR2 + monocytes to the TME." (PMID 41497137, 2026). "For example, CXCL9 and CXCL10 recruit effector T cells into the tumor via CXCR319, 20, promoting anti-tumor responses, while CCL2 recruits MDSCs through CCR2, thereby inhibiting immune responses." (PMID 41399390, 2026). "Previous research has demonstrated that CCR2, by binding to its ligand CCL2, drives the migration of CD14+ CD16+ monocytes from the peripheral blood to tumor sites, constituting a key pathway for immune cell recruitment to the TME." (PMID 41497137, 2026). "CAR-T cells can be engineered to express receptors that are specific to chemokines, including C-C motif chemokine receptor 2 (CCR2) and CCR4, which support efficient contact with tumor cells." (PMID 39996811, 2025). "Importantly, though, with our PCLS and in situ data, we cannot distinguish whether the ZEB1-dependent CTL abundance (in situ) and the CCR2/CCR4-dependent tumor control (PCLS) are regulated by a direct recruitment of CD8 + T cells by CCL2 and/or CCL22 or other alternative mechanisms." (PMID 40595293, 2025). "Targeting key inflammatory mediators—such as the CCL2/CCR2 axis, CSF1R, or the IL-1β signaling pathway—has demonstrated promising anti-tumor effects in preclinical models." (PMID 40881678, 2025). "Targeting monocyte recruitment pathways, such as C-C motif ligand 2/C-C motif chemokine receptor 2 (CCL2/CCR2), has shown promise in reducing tumor infiltration by monocyte-derived macrophages." (PMID 40098971, 2025). "CCL2, secreted by tumor and stromal cells, recruits CCR2+ monocytes, promoting TAM differentiation; anti-CCL2 antibodies reduce TAM infiltration and tumor progression." (PMID 40936918, 2025). "We show that CCR2-armed CAR-T cells (4H11-CCR2) exhibit improved trafficking in vitro, improved trafficking and disease control in vivo and increased survival in peritoneal EOC tumor-bearing mice." (PMID 41424784, 2025).